CD47 (CD47 molecule)
Diseases named in the same sentence as CD47 in open-access papers (continued):
Sharing a sentence is not in itself a finding about the gene and the disease.
thyroid cancer (10 papers, 2012 to 2024). "Conversely, CD47 expression was associated with a more favorable prognosis in skin melanoma or thyroid carcinoma." (PMID 38493445, 2024). "In this list, we found that hsa-mir-507 has a corresponding protein complex, corum-1422, and hsa-mir-221-222 cluster regulates nine protein complexes, of which ITGB1, ITGB3 and CD47 were associated with the thyroid cancer." (PMID 29351231, 2018). "Based on these data, we selected 8505C cells to identify genes that are differentially regulated by CD47 or IFT57 in thyroid cancers." (PMID 39201643, 2024). "In vivo results showed that the expression of CD47 and PD-L1 in thyroid cancer tissues was decreased in response to JHU-083 treatment." (PMID 38386265, 2024). "Our data suggest that DON or JHU-083 down-regulated the expression of CD47 and PD-L1 in thyroid cancer, which was due to protein synthesis inhibition by DON." (PMID 38386265, 2024). "In contrast, most of the genes identified to be dependent for their mRNA expression only on IFT57 in thyroid carcinoma cells were nonetheless significantly coexpressed with CD47 and IFT57 in papillary thyroid tumors." (PMID 39201643, 2024). "Transcriptome analysis following knockdown of CD47 or IFT57 in thyroid carcinoma cells identified the cytoskeletal regulator CRACD as a specific target of IFT57." (PMID 39201643, 2024). "The coregulation of IFT57 with CD47 defined here in thyroid carcinomas generalizes to survival effects in some additional cancer types but is not universal to all malignancies." (PMID 39201643, 2024). "This concept was proven pre-clinically, where blocking CD47 in human thyroid cancer cell lines showed apoptotic effects." (PMID 29455653, 2018). "Generally, most cancer cells, including thyroid cancers, were found to express an inhibitory receptor coined CD47, whose ligand is TAM signal-regulatory protein α (SIRPα)." (PMID 29455653, 2018). "The present results identify distinct gene sets that are regulated by decreasing the expression of CD47 or IFT57 in thyroid carcinoma cells in vitro, but many of these genes exhibit strong correlations with both CD47 and IFT57 mRNA expression in thyroid tumors." (PMID 39201643, 2024). "Although expression of these genes was sensitive to loss of IFT57 but not CD47 in thyroid carcinoma cells, a majority showed positive or negative coexpression with CD47 mRNA in the tumors that paralleled their IFT57 coexpression (e.g., RAMP1)." (PMID 39201643, 2024). "Finally, to find prognostic makers of THCA, we performed survival correlation analysis on all genes in samples of thyroid cancer patients, and finally determined five hub genes based on the log-rank value: CD47, CILP, DERA, KLHL33, PSMB8." (PMID 34376710, 2021). "Among twelve predicted genes, PDGFRA and CD47 had been studied in thyroid cancer." (PMID 25405731, 2014). "Similarly, treatment of MDA-T68 thyroid carcinoma cells with 10 μM JQ1 significantly decreased mRNA for long and short isoforms of CD47, with a parallel time-dependent decreasing trend in mRNA expression for IFT57 mRNA." (PMID 39201643, 2024). "CD47 and IFT57 mRNA expression were consistently higher in 8505C anaplastic thyroid carcinoma cells relative to Nthy-ori-3-1 normal thyroid follicular epithelial cells and other available thyroid carcinoma cell lines." (PMID 39201643, 2024). "This divergence could involve upstream factors that modulate IFT57 target genes secondary to coregulating CD47 and IFT57 expression either in the thyroid carcinoma cells or in tumor stromal cells." (PMID 39201643, 2024). "IFT57 and CD47 mRNA expression were positively correlated across the 11 thyroid carcinomas but did not achieve significance (R2 = 0.18, p = 0.2)." (PMID 39201643, 2024). "CD47 and IFT57 mRNAs were coordinately regulated in thyroid carcinoma cell lines." (PMID 39201643, 2024).
thyroid cancer (continued). "In terms of thyroid cancer, there were two predicted target genes: PDGFRA, functioning as a tumor progression promoter, and CD47, which may influence the radiation reaction of thyroid cell." (PMID 25405731, 2014). "However, another peptide, 4 N1 (RFYVVMWK), which is also derived from the CD47/IAP-binding domain and has a similar structure to the 4N1K peptide (KRFYVVMWKK), has been shown to inhibit apoptosis of human thyroid cancer cells." (PMID 22928942, 2012). "We identified several genes that are specifically regulated by IFT57 but not CD47 knockdown in the 8505C thyroid carcinoma cells, and of these, CRACD showed the highest specificity for dependence on IFT57 but not CD47 mRNA expression in papillary thyroid tumors." (PMID 39201643, 2024).
Alzheimer disease (9 papers, 2010 to 2025). A progressive, neurodegenerative disease characterized by loss of function and death of nerve cells in several areas of the brain leading to loss of cognitive function such as memory and language. "In another recent study, CD47 has been exploited as part of a long-circulating delivery drug (CRT-CD47-NP-Nec-1s) in the treatment of Alzheimer's disease." (PMID 38125492, 2023). "CD47 in Alzheimer's disease has been shown that CD47 facilitates Aβ oligomers internalization by microglia." (PMID 38125492, 2023). "Clearly, microglia-targeted drug delivery with CD47 participation is very helpful for Alzheimer's disease treatment." (PMID 38125492, 2023). "Overexpression of CD47 inhibits microglia engulfment in ASD, whereas the loss of its microglial receptor, Signal Regulatory Protein Alpha (SIRPα), enhances synaptic pruning in Alzheimer’s disease (AD)." (PMID 40238451, 2025). "Our study provides evidence that neuronal CD47 overexpression results in synaptic pruning defects and is involved in the pathogenesis of ASD, while also playing a beneficial role in mitigating excessive synaptic loss in Alzheimer’s disease." (PMID 40140948, 2025). "CD172a, also known as the signal regulatory protein A (SIRPa), is an inhibitory receptor that binds to “do not eat me” ligand CD47 on healthy neurons and loss of CD172a from microglia have led to synaptic pruning in mouse models of Alzheimer’s disease." (PMID 39334169, 2024). "Recognizing that Aβ inhibits NO signaling by suppressing sGC activity through CD36 and CD47 may clarify Aβ's role in Alzheimer's disease pathogenesis and could lead to novel therapeutics aimed at limiting the adverse effects of Aβ in the brain." (PMID 21203512, 2010). "It has been found that CD47–SIRPα signaling could protect synapse from excess microglia-mediated phagocytosis in developing retinogeniculate system, as well as in model of Alzheimer’s disease." (PMID 35360151, 2022). "Moreover, CD47 has been shown to interact with amyloid beta peptide in Alzheimer's disease." (PMID 22369239, 2012).
Autoimmunity (9 papers, 2017 to 2025). The occurrence of an immune reaction against the organism's own cells or tissues. "Altogether, these data suggest that SIRPα:CD47 signaling is particularly important for regulating immune responses in the context of cancer, infectious challenge and potentially, β-cell stress in subjects with high genetic risk for autoimmunity and specifically, T1D." (PMID 34603322, 2021). "Immune inhibitory surface proteins such as CTLA4, CD47, and SIRPα, among many others, provide a means for limiting autoimmunity." (PMID 38543910, 2024). "The outcome could be countered by the undesirable effects of CD47 ECD binders on autoimmunity, which are shared with other checkpoint-blocking molecules, and by agnostic signaling via CD47 in non-cancer cells that limits essential processes." (PMID 41511354, 2025). "Herein, we initially identified a set of 12 surface molecules, including CD39, CD229, CD81, CD326, CD54, CD130, CD49d, CD172a, CD274, CD155, CD205, and CD47 that are highly expressed by ASCs, and specifically identify ASCs in naive WT mice as well as in the contexts of immunization and autoimmunity." (PMID 35464469, 2022). "We pose that the SIRP:CD47 signaling pathway could be an important element in the regulation of autoimmunity." (PMID 34603322, 2021). "Therefore, Epo-dependent regulation of CD47 in new RBCs creates a switch between silent and immune phagocytosis and makes both neocytolysis and homeostatic autoimmunity reversible processes." (PMID 28484605, 2017). "More studies are required to understand how SIRPs:CD47 signaling affects priming and activation of CD4+ and CD8+ T cells, and the corresponding implications for T cell-mediated autoimmunity and T1D pathogenesis." (PMID 34603322, 2021). "Moreover, targets such as CD37, CD47, B7-H6, CDC27, TCRVβ, and CCR8, when employed in CAR-T cells, present minimal risks of fratricide and autoimmunity." (PMID 38915099, 2024). "We suggest that EPO could also regulate RBC lifespan through its effects on CD47 and SIRP-α expression and through EPO-induced autoimmunity." (PMID 38191841, 2024). "The effect of EPO on CD47 and SIRP-α would also lead to changes in the autoimmunity threshold." (PMID 38191841, 2024). "First, changes in CD47 expression in newly formed RBCs could account for differences in lifespan observed in erythrophagocytosis and neocytolysis, as well as for the origin and function of anti-RBC autoimmunity." (PMID 28484605, 2017).
colitis (9 papers, 2015 to 2025). Inflammation of the colon. "Functional experiments demonstrate that NR1D1 deficiency enhances epithelial apoptosis, upregulates CD47, impairs macrophage efferocytosis, and exacerbates colitis in IEC‐specific Nr1d1−/− mice." (PMID 41163542, 2025). "The CD47 expression in IECs is correlated with the severity of colitis, and CD47 deficiency protects mice from DSS-induced colitis." (PMID 32576895, 2020). "In conclusion, our resultshave demonstrated that CD47 deficiency protects intestinal epithelium against colitis by promoting proliferation and self-renewal of IEC and maintaining the intergrity of the epithelial barrier." (PMID 32576895, 2020). "Based on these results, we conclude that CD47 deficiency relieves the colitis mainly by enhancing the proliferation of the IEC which are the keys to cell recovery following the damage and cell apoptosis induced by DSS or proinflammatory cytokines." (PMID 32576895, 2020). "Although chronic inflammation with less neutrophil production or lower percentage of SIRPα+CD103− DCs and Th17 responses have been suggested to contribute to the resistance of CD47−/− mice to experimental colitis, the underlying mechanism remains elusive." (PMID 32576895, 2020). "CD47 deficient mice are resistant to dextran sulfate sodium (DSS)-induced experimental colitis." (PMID 32576895, 2020). "Given that CD47 deficiency significantly relieved DSS-induced colitis, downregulation of CD47 expression in the IEC may improve the condition of IBD." (PMID 32576895, 2020). "In line with this, CD47 deficiency protected mice from DSS-induced colitis." (PMID 32576895, 2020). "Pharmacological activation of NR1D1 using a bioadhesive hydrogel delivering SR9011 restores intestinal immune balance, reduces CD47 expression, and ameliorates colitis severity." (PMID 41163542, 2025). "Specifically, we show that SR9011‐activated NR1D1 reduces CD47 expression, enhances macrophage‐mediated clearance of apoptotic cells, and significantly improves disease outcomes in a murine colitis model." (PMID 41163542, 2025). "While selective intestinal knockout of CD47 resulted in decreased mucosal healing following DSS colitis and biopsy wounding, it was shown that CD47 regulates mucosal repair again through a β1 integrin-dependent FAK-Src-p130Cas pathway." (PMID 35937599, 2022). "In the present study, we found that CD47 expression is significantly increased in patients with UC and CD as well as in mouse experimental colitis models." (PMID 32576895, 2020). "Disease activity index, tissue section examination and histological scoring also clearly showed that CD47−/− mice displayed less intestinal epithelial tissue damage during DSS-induced experimental colitis." (PMID 32576895, 2020). "Similar to observations in intestinal tissue samples from IBD patients, CD47 upregulation in IECs was also detected in DSS-induced murine experimental colitis model." (PMID 32576895, 2020). "Our studies thus reveal CD47 as a negative regulator in intestinal epithelial cell renewal during colitis through downregulating OSKM transcriptional factors." (PMID 32576895, 2020). "Colitis/DAI was more pronounced following induced deletion of CD47 in tamoxifen-treated Cd47ERΔIEC mice." (PMID 31676794, 2019). "An IL-17- and G-CSF-dependent deficit in granulopoiesis in cd47-/- mice was reported in the colitis model, but we observed increased neutrophils and macrophages/monocytes in infected cd47-/- kidneys and neutrophils in infected brains." (PMID 26010544, 2015). "Lower IL-17 is also consistent with a diminished Th17 response reported in cd47-null mice exposed to trinitrobenzene sulfonic acid in a colitis model." (PMID 26010544, 2015). "This is consistent with a previous report of diminished serum IL-6 and IL-17A levels in cd47-/- mice in a dextran sulfate-induced colitis model." (PMID 26010544, 2015).
colitis (continued). "In DSS‐induced colitis, hydrogel‐mediated SR9011 suppresses inflammation, reduces CD47, preserves epithelial integrity, and improves histological outcomes." (PMID 41163542, 2025). "Ongoing research indicates that antagonizing the CD47-SIRPA interaction can alleviate clinical symptoms in arthritis, colitis, and Crohn’s disease, making the CD47-SIRPA axis a potential therapeutic target for these conditions." (PMID 38835033, 2024). "Additional reports showed that CD47/SIRP-alpha interaction participated in the development of ischemia reperfusion-induced acute kidney injury, colitis and allergic asthma." (PMID 35634325, 2022). "CD47 expression in the colon is strongly induced in patients with UC and CD and in mouse with DSS-induced experimental colitis." (PMID 32576895, 2020).
colon adenocarcinoma (9 papers, 2018 to 2026). "The surface of drug-loaded nanocage was further tattooed with MnO2 mineralization and electrostatically modified with αPD-L1 or anti-CD47 antibody (αCD47) for the treatment of TNBC and colon adenocarcinoma (COAD), respectively." (PMID 36341334, 2022).
hematoma (9 papers, 2021 to 2025). A hematoma is a collection of blood from a vascular structure into an extravascular space. "For example, injection of CD47-deficient blood or CD47 antibody administration lead to faster hematoma clearance and reduced secondary brain injury after intracerebral hemorrhage." (PMID 38125492, 2023). "Animals that are genetically deficient in CD47 or those administered CD47 inhibiting antibodies have accelerated hematoma clearance, reduction in brain edema, reduced neuronal death and improved functional outcomes in ICH models." (PMID 35365172, 2022). "CD47, an integrin-associated protein expressed on erythrocytes, has been demonstrated to regulate hematoma clearance in the ICH model." (PMID 34685493, 2021). "Enhancing microglial/macrophage erythrophagocytosis throughactivation of TAM receptors, CD36, and TREM2 or inhibition of theSIRPα-CD47 pathway plays a central role in promoting hematoma clearanceand mitigating secondary brain injury." (PMID 41504200, 2025). "Intracranial injection of CD47 knockout blood accelerates hematoma resolution and reduces brain edema, effects attenuated by intracranial clodronate liposome administration, a specific Mφ depletion agent." (PMID 39660125, 2024). "In nude mice injected with blood from CD47 knockout or wild-type mice, CD47 knockout blood had quicker hematoma absorption than wild-type blood at 3 days after ICH." (PMID 37601043, 2023). "Intracranial injection of CD47 knock-out blood resulted in quicker hematoma resolution and milder brain edema." (PMID 35237132, 2022). "Blocking CD47 accelerates hematoma removal by promoting erythrophagocytosis by macrophages, and injection of CD47 knockout blood also favors clot resolution when compared to WT blood in ICH." (PMID 35966018, 2022). "Co-injection of the CD47 blocking antibody accelerated hematoma clearance and reduced hemolysis visualized within the hematoma." (PMID 35365172, 2022). "Furthermore, CD47 blocking antibodies significantly enhance erythrophagocytosis and promote hematoma clearance following ICH." (PMID 39660125, 2024). "In all, CD47 may serve as an inhibitory signal in Mφ-mediated hematoma resolution." (PMID 35237132, 2022). "In contrast, during the chronic recovery phase, “anti‐inflammatory” (M2‐type) microglia aid in hematoma resolution and tissue repair by phagocytosing cellular debris and engaging in receptor‐mediated clearance via CD163, CD36, and CD47." (PMID 40994248, 2025). "Inspiringly, CD47 blocking antibody significantly enhanced hematoma removal after ICH, rendering CD47 a promising and draggable target in ICH treatment." (PMID 35237132, 2022).
mantle cell lymphoma (9 papers, 2020 to 2025). Mantle cell lymphoma is a rare form of malignant non-Hodgkin lymphoma affecting B lymphocytes in the lymph nodes in a region called the ``mantle zone''. "The anti-LILRB1 antibody was found to significantly enhance ADCP when combined with CD20 and CD47 antibodies by analyzing different B-NHL cell lines and tumor cells from chronic lymphocytic leukemia (CLL) or mantle cell lymphoma (MCL) patients." (PMID 36389667, 2022). "In mantle cell lymphoma (MCL) and follicular lymphoma patients, high mRNA expression of CD24 correlated with poor overall survival, whereas CD47 expression did not." (PMID 35625912, 2022).